CIB1 (calcium and integrin binding 1)
Description:
Calcium-binding protein that plays a role in the regulation of numerous cellular processes, such as cell differentiation, cell division, cell proliferation, cell migration, thrombosis, angiogenesis, cardiac hypertrophy and apoptosis. Involved in bone marrow megakaryocyte differentiation by negatively regulating thrombopoietin-mediated signaling pathway. Participates in the endomitotic cell cycle of megakaryocyte, a form of mitosis in which both karyokinesis and cytokinesis are interrupted. Plays a role in integrin signaling by negatively regulating alpha-IIb/beta3 activation in thrombin-stimulated megakaryocytes preventing platelet aggregation. Up-regulates PTK2/FAK1 activity, and is also needed for the recruitment of PTK2/FAK1 to focal adhesions; it thus appears to play an important role in focal adhesion formation. Positively regulates cell migration on fibronectin in a CDC42-dependent manner, the effect being negatively regulated by PAK1. Functions as a negative regulator of stress activated MAP kinase (MAPK) signaling pathways. Down-regulates inositol 1,4,5-trisphosphate receptor-dependent calcium signaling. Involved in sphingosine kinase SPHK1 translocation to the plasma membrane in a N-myristoylation-dependent manner preventing TNF-induced apoptosis. Regulates serine/threonine-protein kinase PLK3 activity for proper completion of cell division progression. Plays a role in microtubule (MT) dynamics during neuronal development; disrupts the MT depolymerization activity of STMN2 attenuating NGF-induced neurite outgrowth and the MT reorganization at the edge of lamellipodia. Promotes cardiomyocyte hypertrophy via activation of the calcineurin/NFAT signaling pathway. Stimulates calcineurin PPP3R1 activity by mediating its anchoring to the sarcolemma. In ischemia-induced (pathological or adaptive) angiogenesis, stimulates endothelial cell proliferation, migration and microvessel formation by activating the PAK1 and ERK1/ERK2 signaling pathway. Also promotes cancer cell survival and proliferation. May regulate cell cycle and differentiation of spermatogenic germ cells, and/or differentiation of supporting Sertoli cells. Forms a complex with TMC6/EVER1 and TMC8/EVER2 in lymphocytes and keratynocytes where CIB1 stabilizes TMC6 and TMC8 levels and reciprocally. Acts as a restriction factor that promotes keratinocyte-intrinsic immunity to human beta-papillomaviruses (HPVs). [Isoform 2]: Plays a regulatory role in angiogenesis and tumor growth by mediating PKD/PRKD2-induced vascular endothelial growth factor A (VEGFA) secretion.
Synonyms: CIB; CIBP; KIP; SIP2-28; PRKDCIP; EV3; KIP1
Tractability: Antibody: its Gene Ontology location is reachable by antibodies, with high confidence; UniProt places it where antibodies can reach, with medium confidence; the Human Protein Atlas places it where antibodies can reach. PROTAC: ubiquitination databases record sites on it; its protein half-life has been measured; a small molecule that binds it is known.
Gene: Protein-coding gene on chromosome 15 (90,229,975 to 90,234,047, reverse strand). Ensembl gene ENSG00000185043.
Subcellular location: Membrane; Cell membrane, sarcolemma; Cell membrane; Apical cell membrane; Cell projection, ruffle membrane; Cell projection, filopodium tip; Cell projection, growth cone; Cell projection, lamellipodium; Cytoplasm; Cytoplasm, cytoskeleton; Cytoplasm, cytoskeleton, microtubule organizing center, centrosome; Cytoplasm, perinuclear region; Nucleus; Cell projection, neuron projection; Perikaryon; Cytoplasm, perinuclear region (Isoform 2); Golgi apparatus, trans-Golgi network
Subcellular location (Human Protein Atlas): Nucleoplasm; Plasma membrane; Nuclear bodies
Gene Ontology:
Molecular function: calcium ion binding; calcium-dependent protein kinase inhibitor activity; protein binding; protein serine/threonine kinase inhibitor activity; protein-membrane adaptor activity; small GTPase binding; magnesium ion binding
Biological process: apoptotic process; cellular response to nerve growth factor stimulus; cellular response to tumor necrosis factor; cytoplasmic microtubule organization; DNA damage response; endomitotic cell cycle; negative regulation of apoptotic process; negative regulation of cell population proliferation; negative regulation of microtubule depolymerization; negative regulation of neuron projection development; positive regulation of calcineurin-NFAT signaling cascade; positive regulation of cell adhesion mediated by integrin; positive regulation of protein localization to plasma membrane; positive regulation of protein targeting to membrane; positive regulation of substrate adhesion-dependent cell spreading; regulation of cell division; regulation of cell population proliferation; cell adhesion; cellular response to growth factor stimulus; double-strand break repair; extrinsic apoptotic signaling pathway; negative regulation of megakaryocyte differentiation; negative regulation of phosphatidylinositol 3-kinase/protein kinase B signal transduction; negative regulation of protein phosphorylation; platelet formation; and 13 more
Cellular component: cell periphery; centrosome; cytoplasm; endoplasmic reticulum; extracellular exosome; filopodium tip; growth cone; lamellipodium; membrane; neuron projection; neuronal cell body; nucleoplasm; nucleus; perikaryon; perinuclear region of cytoplasm; plasma membrane; sarcolemma; vesicle; axon; apical plasma membrane; cytoskeleton; Golgi apparatus; ruffle membrane
Genetic constraint (gnomAD): Loss-of-function variants: 19 observed, 22.6 expected, observed/expected ratio (o/e) 0.84, 90% interval 0.58 to 1.23. The upper end of that interval is the gene's LOEUF score, 1.23, which puts it in group 5 of 6, group 1 being the genes least tolerant of losing a copy. Missense variants: 236 observed, 239.31 expected, observed/expected ratio (o/e) 0.99, 90% interval 0.89 to 1.1. Synonymous variants: 104 observed, 95.54 expected, observed/expected ratio (o/e) 1.09, 90% interval 0.93 to 1.28.
Homologues: Orthologues: chimpanzee CIB1 (100% identical), macaque CIB1 (98% identical), mouse Cib1 (94% identical), pig CIB1 (94% identical), rat Cib1 (92% identical), guinea pig CIB1 (88% identical), dog CIB1 (83% identical), zebrafish cib1 (61% identical), tropical clawed frog cib1 (58% identical), Drosophila melanogaster Cib2 (44% identical), Caenorhabditis elegans calm-1 (41% identical), Drosophila melanogaster elm (24% identical), and 4 more. Paralogues in human: CIB4 (41% identical), CIB3 (39% identical), CIB2 (36% identical), PPP3R1 (25% identical), PPP3R2 (25% identical), CHP1 (23% identical), TESC (23% identical), CHP2 (21% identical).
Diseases named in the same sentence as CIB1 in open-access papers:
CIB1 is named in the same sentence as 54 diseases in open-access papers, as found by Europe PMC text mining. Sharing a sentence is not in itself a finding about the gene and the disease. The quoted sentences say what the papers report.
breast carcinoma (10 papers, 2014 to 2025). "In MDA-MB-468 human breast cancer cells, macrophages supplied with calcium integrin binding protein-1 (CIB1)-siRNA reduced tumorsphere development and CIB1 and KI67 mRNA expression." (PMID 40943069, 2025). "CIB1 regulates cancer cell migration, proliferation, and survival in vitro and promotes tumor growth in breast cancer models in vivo." (PMID 40076845, 2025). "In MDA-MB-468 human breast cancer cells, the macrophage-mediated delivery of CIB1-targeting siRNA significantly attenuated tumor spheroid growth, accompanied by marked reductions in both CIB1 and KI67 mRNA expression levels." (PMID 40076845, 2025). "In addition, we confirmed macrophages horizontal transfer of siRNA can result in therapeutic effect as evidenced by decreased tumorsphere growth via delivery of CIB1‐siRNA to MDA‐MB‐468 breast cancer cells." (PMID 31728272, 2019). "In particular, CIB1 has been shown to function as a Ca2+‐sensitive negative regulator of ASK1 (apoptosis signal‐regulating kinase‐1)‐mediated signalling events, involved in cell survival, and CIB1 depletion in breast cancer cell lines results in significant cell death." (PMID 29084757, 2017). "In aggressive breast cancer, RAC3’s specific binding partner CIB1 facilitates the recruitment of RAC3, promoting integrin activation at invasive pseudopodia, thereby regulating adhesion and degradation of the extracellular matrix (ECM)." (PMID 39872053, 2024). "Macrophages loaded with calcium integrin binding protein‐1 (CIB1)‐siRNA result in decreased tumorsphere growth and decreased mRNA expression of CIB1 and KI67 in MDA‐MB‐468 human breast cancer cells." (PMID 31728272, 2019). "CIB1 has been shown to promote megakaryocyte migration towards SDF-1α and expression of CIB1 has been reported to be upregulated in breast cancer tissue suggesting a regulatory role for CIB1 in cell migration." (PMID 25200405, 2014).
triple-negative breast carcinoma (6 papers, 2019 to 2025). An invasive breast carcinoma which is negative for expression of estrogen receptor (ER), progesterone receptor (PR), and human epidermal growth factor receptor 2 (HER2). "We employ FRASE-bot to identify ligands for CIB1, a protein implicated in triple negative breast cancer." (PMID 38956119, 2024). "We apply FRASE-bot to identify ligands for Calcium and Integrin Binding protein 1 (CIB1), a promising drug target implicated in triple negative breast cancer." (PMID 38956119, 2024). "Previous studies showed that CIB1 depletion induces cell death and inhibition of CIB1-dependent signaling in 8 of 11 of triple-negative breast cancer cell lines." (PMID 37645935, 2023). "The new method was applied to identify potential agents against Triple Negative Breast Cancer (TNBC) by targeting Calcium- and Integrin-Binding Protein 1 (CIB1) 30–32." (PMID 37645935, 2023). "CIB1 has been proven to be involved in the progression of triple-negative breast cancer and lung adenocarcinoma and has gradually been considered important in maintaining cell survival and proliferation." (PMID 37187730, 2023). "Here, FRASE-bot was applied to identify ligands for Calcium and Integrin Binding protein 1 (CIB1), a promising but ligand-orphan drug target implicated in triple negative breast cancer." (PMID 37645935, 2023). "CIB1 has emerged as a promising therapeutic target in triple-negative breast cancer pathogenesis." (PMID 40076845, 2025).
ischemia (3 papers, 2010 to 2014). A hypoperfusion of the BLOOD through an organ or tissue caused by a PATHOLOGIC CONSTRICTION or obstruction of its BLOOD VESSELS, or an absence of BLOOD CIRCULATION. "Depletion of CIB1 in endothelial cells results in decreased PAK1 activation and impaired endothelial cell function, and we have previously reported that CIB1−/− mice exhibit impaired ischemia-induced angiogenesis in retinal and hindlimb tissue concomitant with a decrease in PAK1 activation." (PMID 25379771, 2014). "CIB1 is a calcium and integrin-binding protein-1 that is essential for proper EC signaling and function such as migration, proliferation, and nascent tubule formation, and therefore is critical in ischemia-induced angiogenesis in the retina, as well as ischemia-induced adaptive angiogenesis." (PMID 24672479, 2014). "Previously we found that CIB1, a 22 kDa regulatory protein, plays a critical role in endothelial cell function, angiogenic growth factor-mediated cellular functions, PAK1 activation, MMP-2 expression, and in vivo ischemia-induced angiogenesis." (PMID 20804551, 2010).
viral infection (3 papers, 2016 to 2020). "These molecules were found to be associated with KSHV, EphA2R and CIB1 early during viral infection." (PMID 27764233, 2016). "CIB1 and CIB2 knockdown were shown to reduce the expression of surface receptors implicated in HIV-1 infection, suggesting at least one mechanism through which these proteins promote viral infection." (PMID 27489023, 2016). "In conclusion, our work demonstrates that knockdown of both CIB1 and CIB2 impaired an early step in receptor-mediated viral entry involved in both cell-free and cell-mediated viral infection, and was associated with reduced surface expression of CXCR4, CCR5 and α4β7." (PMID 27489023, 2016). "CIB1 and CIB2 knockdown was found to reduce the expression of surface molecules implicated in HIV-1 infection, including CXCR4, CCR5 and integrin α4β7, suggesting at least one mechanism through which these proteins promote viral infection." (PMID 27489023, 2016). "Interestingly, HPV4 E8 interacts with CIB1, suggesting that this virus may interfere with EVER1/EVER2/CIB1-dependent restriction of viral infection." (PMID 32222599, 2020). "Knockdown of both CIB1 and CIB2 impaired an early step in receptor-mediated viral entry, and both cell-free and cell-mediated viral infections were affected." (PMID 27489023, 2016). "Taken together, our results indicate that the effects of CIB1 and CIB2 knockdown specifically affect early events in virus infection, encompassing receptor-mediated viral binding, membrane fusion, and possibly, early post-fusion modification of the cellular cytoskeleton." (PMID 27489023, 2016). "Taken together, these results indicate that both CIB1 and CIB2 play an important and non-redundant role in facilitating viral infection of Jurkat T-cells." (PMID 27489023, 2016).
atrial fibrillation (2 papers, 2016 to 2025). A disorder characterized by an electrocardiographic finding of a supraventricular arrhythmia characterized by the replacement of consistent P waves by rapid oscillations or fibrillatory waves that vary in size, shape and timing and are accompanied by an irregular ventricular response. "Furthermore, CIB1 contributes to atrial pathophysiology, as evidenced by its elevated expression in the right atrial myocardium of atrial fibrillation patients." (PMID 40076845, 2025). "Moreover, numerous studies have implicated the paralogue CIB1 (38% identical and 59% similar to CIB2), in cardiac hypertrophy and atrial fibrillation, and in valvular heart disease." (PMID 26378684, 2016).
epidermodysplasia verruciformis (2 papers, 2025). A rare inherited genodermatosis characterized by chronic infection with human papillomavirus (HPV) leading to polymorphous cutaneous lesions and high risk of developing non melanoma skin cancer. "Typical epidermodysplasia verruciformis (EV) patients carry biallelic disabling mutations in TMC6, TMC8 or CIB1, and suffer high rates of skin cancer in UV-exposed sites associated with human betapapillomavirus (βHPV)+ plane warts." (PMID 39813296, 2025).
lung adenocarcinoma (2 papers, 2021 to 2023). A carcinoma that arises from the lung and is characterized by the presence of malignant glandular epithelial cells. "All those indicated that CIB1 is negatively regulated by CHIP and affects the metastatic ability of lung adenocarcinoma cells in vitro." (PMID 33082516, 2021). "The interaction of CIB1 and CHIP then controlled the invasion and migration of lung adenocarcinoma." (PMID 33082516, 2021). "Thus, we proved that CIB1 can negatively be regulated by CHIP and affects the metastatic ability of lung adenocarcinoma cells in vivo." (PMID 33082516, 2021).
ovarian carcinoma (2 papers, 2017). A malignant neoplasm originating from the surface ovarian epithelium. "Also, a recent study showed that similar to CIB1, CIB2 negatively regulates oncogenic signalling in ovarian cancer via its interaction with sphingosine kinase 1 (SK1), a regulator of the cellular balance between pro‐apoptotic and pro‐survival sphingolipids." (PMID 29084757, 2017).
pancreatic cancer (2 papers, 2023). "In this study, we found that CIB1 was widely co-expressed with KRAS mutation in pancreatic cancer cell lines and upregulated in tumor samples." (PMID 37187730, 2023).
basosquamous carcinoma (1 paper, 2023). A basal cell carcinoma which displays squamous differentiation. "One family with a CIB1 mutation has been reported with basosquamous carcinoma, and pathology revealed infiltrative malignant cells with both basaloid and squamous differentiation." (PMID 36602881, 2023).
bladder cancer (1 paper, 2023).
COVID-19 (1 paper, 2023). A disease caused by infection with severe acute respiratory syndrome coronavirus 2. "It was revealed that three hub CORGs (ENTPD6, CIB1, and EIF3B) had good diagnostic performance to discriminate COVID-19/MI and control samples (AUC > 0.75)." (PMID 37020555, 2023). "Our results showed the significant change of CIB1 in sequencing and experimental data, and that it may have the potential as a biomarker for COVID-19-induced spermatogenesis impairment." (PMID 37020555, 2023). "It is noted that two hub genes (CIB1 and EIF3B) had the significant change pattern in the sequencing findings and qRT-PCR results, emphasizing the critical genetic links of CIB1 and EIF3B between COVID-19 and MI." (PMID 37020555, 2023).
hearing loss (1 paper, 2018). "Our biochemical and biophysical study highlights a number of clear structural and functional differences with CIB1, which may thus pose the molecular basis for understanding the malfunctioning of CIB2 in USH1J and possibly other genetic diseases causing hearing loss." (PMID 30174586, 2018).
HIV-1 infection (1 paper, 2016). The type species of lentivirus and the etiologic agent of acquired immunodeficiency syndrome (AIDS). "The efficiency of HIV-1 infection can be improved by cell-to-cell transmission, raising the possibility that cell-to-cell transmission would abrogate the defect in infectivity seen following downmodulation of CIB1 and CIB2 expression." (PMID 27489023, 2016). "To palliate this uncertainty, we have undertaken a series of studies to better define the role of CIB1 and CIB2 in HIV-1 infection." (PMID 27489023, 2016). "We found, however, that the viability of Jurkat cells and activated CD4+ T-lymphocytes either before or after HIV-1 infection was not influenced by CIB1 and CIB2 knockdown." (PMID 27489023, 2016).
Immunodeficiency (1 paper, 2022). Failure of the immune system to protect the body adequately from infection, due to the absence or insufficiency of some component process or substance. "Interestingly, CIB1 has also been reported to bind WASP, a protein with mutations in patients with the immunodeficiency Wiskott-–Aldrich syndrome; the WASP–CIB1 complex was assigned a role in integrin αIIbβ3-dependent cell adhesion." (PMID 35955827, 2022).
Infertility (1 paper, 2025). "Similar to CIB1-knockout mice, Cib4-knockout mice exhibited impaired haploid differentiation during spermatogenesis and infertility." (PMID 40076845, 2025). "Together, these findings highlight the critical role of CIB1 and CIB4 in male fertility and their potential involvement in infertility." (PMID 40076845, 2025).
Lewis lung carcinoma (1 paper, 2010). "To test this hypothesis, we allografted either murine B16 melanoma or Lewis lung carcinoma cells into WT and CIB1-KO mice, and monitored tumor growth, morphology, histology, and intra-tumoral microvessel density." (PMID 20804551, 2010). "Similarly, allografted Lewis lung carcinoma tumors in CIB1-KO mice were smaller in volume and mass, and appeared to have decreased perfusion." (PMID 20804551, 2010).
lung carcinoma (1 paper, 2021). "The previous report has found that Integrin, a binding protein of CIB1, plays an important role in the development of lung cancer by participating in EMT." (PMID 33082516, 2021).
lymph node metastasis (1 paper, 2021). "What’s more, CIB1 expression was significantly higher in LAC with lymph node metastasis and advanced stage." (PMID 33082516, 2021).